VSIG10L2 (V-set and immunoglobulin domain containing 10 like 2)
Tractability: Antibody: UniProt predicts a signal peptide or a membrane-spanning region; its Gene Ontology location is reachable by antibodies, with medium confidence.
Gene: Protein-coding gene on chromosome 11 (125,946,044 to 125,958,647, forward strand). Ensembl gene ENSG00000283703.
Subcellular location: Membrane
Gene Ontology:
Molecular function: cell adhesion molecule binding
Biological process: cell-cell adhesion
Cellular component: cell-cell junction; plasma membrane; membrane
Genetic constraint (gnomAD): Loss-of-function variants: 51 observed, 54.76 expected, observed/expected ratio (o/e) 0.93, 90% interval 0.74 to 1.18. The upper end of that interval is the gene's LOEUF score, 1.18, which puts it in group 5 of 6, group 1 being the genes least tolerant of losing a copy. Missense variants: 805 observed, 798.5 expected, observed/expected ratio (o/e) 1.01, 90% interval 0.95 to 1.07. Synonymous variants: 347 observed, 337.39 expected, observed/expected ratio (o/e) 1.03, 90% interval 0.94 to 1.12.
Homologues: Orthologues: chimpanzee VSIG10L2 (96% identical), macaque VSIG10L2 (93% identical), pig VSIG10L2 (78% identical), guinea pig VSIG10L2 (77% identical), mouse Vsig10l2 (73% identical), rat Vsig10l2 (71% identical).